BRI3BP (BRI3 binding protein)
Synonyms: KG19; BNAS1; HCCR-2; HCCRBP-3; HCCR-1; HCCRBP-1
Tractability: Antibody: UniProt predicts a signal peptide or a membrane-spanning region. PROTAC: ubiquitination databases record sites on it; its protein half-life has been measured.
Gene: Protein-coding gene on chromosome 12 (124,993,645 to 125,031,231, forward strand). Ensembl gene ENSG00000184992.
Subcellular location: Mitochondrion outer membrane
Subcellular location (Human Protein Atlas): Mitochondria; Nucleoplasm
Gene Ontology:
Molecular function: protein binding
Cellular component: mitochondrion; mitochondrial outer membrane
Genetic constraint (gnomAD): Loss-of-function variants: 7 observed, 11.96 expected, observed/expected ratio (o/e) 0.59, 90% interval 0.33 to 1.1. The synonymous counts are far from expectation, so gnomAD's model fits this gene poorly and the ratio says little. Missense variants: 299 observed, 291.39 expected, observed/expected ratio (o/e) 1.03, 90% interval 0.93 to 1.13. Synonymous variants: 178 observed, 140.59 expected, observed/expected ratio (o/e) 1.27, 90% interval 1.12 to 1.43.
Homologues: Orthologues: chimpanzee BRI3BP (100% identical), macaque BRI3BP (99% identical), dog BRI3BP (88% identical), pig BRI3BP (86% identical), guinea pig BRI3BP (84% identical), mouse Bri3bp (82% identical), rat Bri3bp (80% identical), tropical clawed frog bri3bp (58% identical), zebrafish bri3bp (53% identical).
Diseases named in the same sentence as BRI3BP in open-access papers:
BRI3BP is named in the same sentence as 6 diseases in open-access papers, as found by Europe PMC text mining. Sharing a sentence is not in itself a finding about the gene and the disease. The quoted sentences say what the papers report.
hepatocellular carcinoma (1 paper, 2025). A malignant tumor that arises from hepatocytes. "The unexpected finding that BRI3BP overexpression lowers lapatinib IC50 is consistent with earlier reports that ROCK-dependent cytoskeletal stress sensitizes hepatoma cells to EGFR inhibition." (PMID 41174063, 2025). "BRI3BP, an RNA-binding protein upregulated in multiple cancers, plays an undefined role in hepatocellular carcinoma (HCC)." (PMID 41174063, 2025).
cancer (3 papers, 2016 to 2025). A tumor composed of atypical neoplastic, often pleomorphic cells that invade other tissues. "Due to its frequent association with aggressive tumors, BRI3BP has become a significant focus of research in cancer studies." (PMID 41174063, 2025). "High BRI3BP expression was positively correlated with various pathways, such as those involving the retinoblastoma gene in cancer, the resolution of sister chromatid cohesion, mitotic prometaphase, Rho GTPase activation of formins, and cell cycle checkpoints." (PMID 41174063, 2025). "In addition, it has been reported that BRI3BP expression is decreased in cancer samples." (PMID 37719132, 2023). "Collectively, the results indicate a complex interplay between BRI3BP and the HCC immune microenvironment, suggesting that BRI3BP may mediate immune evasion or modulation in this cancer." (PMID 41174063, 2025).
tumor (1 paper, 2025). "Furthermore, the observed association between high BRI3BP expression and poor tumor differentiation could potentially confound the results of the pathway enrichment analyses, particularly for metabolic processes." (PMID 41174063, 2025). "BRI3BP expression correlated strongly with immunosuppressive subsets—Th2 cells (r = 0.482, P < 0.001) and CD4 + T cells (r = 0.208, P = 1.00e-04), indicating that BRI3BP may foster an immunosuppressive tumor microenvironment linked to resistance to immune-checkpoint blockade in HCC35." (PMID 41174063, 2025). "Collectively, these data indicate that, in vitro, BRI3BP overexpression is associated with aggressive phenotypes of HCC cells and activates the ROCK signaling pathway, suggesting potential involvement in tumor progression." (PMID 41174063, 2025). "A multivariable-adjusted prognostic nomogram integrating BRI3BP expression, tumor status, and T stage demonstrated robust discriminative accuracy for 1-, 3-, and 5-year OS prediction." (PMID 41174063, 2025). "Notably, in HCC, BRI3BP expression was markedly elevated in tumor tissues compared to normal hepatic tissues (P < 0.001)." (PMID 41174063, 2025). "Additionally, the analysis of methylation patterns demonstrated that BRI3BP exhibited elevated methylation levels in HCC tissues compared to adjacent non-tumor liver tissues." (PMID 41174063, 2025). "BRI3BP was overexpressed in HCC and correlated with advanced tumor stage, shorter overall survival (OS), and disease-free survival (DFS)." (PMID 41174063, 2025). "In vitro, BRI3BP overexpression promoted HCC cell migration and invasion and activated the ROCK signaling pathway, suggesting potential involvement in tumor progression." (PMID 41174063, 2025). "Experimental data indicate that BRI3BP enhances cell migration and invasion and activates the ROCK pathway, highlighting its multifaceted role in tumor biology." (PMID 41174063, 2025). "Mechanistically, BRI3BP activated the ROCK signaling cascade and promoted HCC-cell motility, implicating this pathway in tumor progression." (PMID 41174063, 2025).
BRI3BP also shares sentences with these, for which no sentence is quoted: breast carcinoma (1 paper); cholangiocarcinoma (1); lung squamous cell carcinoma (1).